HIF1A (hypoxia inducible factor 1 subunit alpha)
Diseases named in the same sentence as HIF1A in open-access papers (continued):
Sharing a sentence is not in itself a finding about the gene and the disease.
tumor (continued). "This revealed that levels of hypoxia-inducible factor-1α (HIF1α) were elevated in tumor tissues compared with adjacent benign tissues, consistent with intratumoral hypoxia." (PMID 38537696, 2024). "Hypoxia-inducible transcription factor 1α (HIF-1α), was identified as the main regulator of hypoxia-induced drug resistance and is considered to be an attractive target for tumor therapy." (PMID 37608665, 2024). "Combination therapy with 2‐ME2 and EPZ6438 demonstrated promising antitumor activity in an in vivo A549 xenograft tumor model, suggesting that dual targeting of HIF‐1α and EZH2 is an emerging and attractive therapeutic approach." (PMID 38072662, 2024). "Targeting HIF-1α can enhance the efficacy of immunotherapy by modulating the tumor microenvironment and improving immune responses." (PMID 39493156, 2024). "Previous studies have demonstrated a close relationship between HIF-1α expression and the oxygenation status of tumors, establishing it as a crucial biomarker of tumor hypoxia, invasiveness, or radioresistance." (PMID 39723370, 2024). "Carbonic Anhydrase IX (CA9), an enzyme regulated by HIF1α, facilitates the maintenance of pH balance in hypoxic tumor cells, thereby enhancing cell survival." (PMID 39635662, 2024). "A potential therapeutic approach to stop tumor growth and enhance treatment results is to target HIF-1α." (PMID 39493156, 2024). "Further analysis of the miR-18a targets highlighted possible hypoxia-inducible factor 1-alpha (HIF-1α)-mediated signalling in these tumours." (PMID 38786043, 2024). "On the other hand, curcumin directly represses the activity of HIF-1α and interferes with the metabolic mechanisms of tumor cells." (PMID 37588219, 2024). "Studies have reported that TACE can lead to ischemia and hypoxia in tumor tissue, which upregulates hypoxia-inducible factor-1 alpha (HIF-1α) and induces the upregulation of VEGF, PDGF, FGF, and other factors." (PMID 38298738, 2024). "The Von Hippel–Lindau tumor suppressor regulates HIF-1α, but our focus is on the PHD family, as they are intermediaries between HIF-1α and the Von Hippel–Lindau tumor suppressor." (PMID 38542288, 2024). "Hypoxia-inducible factor 1-alpha (HIF-1α) is necessary for cells to adapt to low oxygen levels often present in the tumor microenvironment." (PMID 39493156, 2024). "In preclinical studies, tumor development has been seen to be significantly impacted by the inhibition of HIF-1α activity by various methods." (PMID 38790642, 2024). "The expression of RUVBL1 and HIF-1α proteins in our cohort was assessed using immunohistochemistry in ccRCC tissue samples and adjacent non-tumor tissues." (PMID 38610951, 2024). "Hypoxia Inducible factor-1 alpha (HIF-1α), which can be induced by hypoxia and many other factors, regulates gene transcription in tumor cells and is corelated with the tolerance of chemotherapy." (PMID 38899007, 2024). "In certain cancers, aberrant HIF-1α or HIF-2α signaling contributes to tumor progression by promoting angiogenesis and metabolic reprogramming." (PMID 39450110, 2024). "Herein, we aimed to investigate the interaction of the PDT and tumor HIF-1α/PD-L1 expression to assess their prognostic values." (PMID 38609977, 2024). "YY1 promotes tumor angiogenesis by stabilizing the hypoxia-inducible factor-1α (HIF-1α) and activating angiogenic factors like vascular endothelial growth factor (VEGF) and transforming growth factor alpha (TGF-α)." (PMID 38893192, 2024). "Hypoxia-inducible factor 1-alpha (HIF1α) is a crucial regulator of cellular adaptation to low oxygen conditions, significantly influencing tumor progression through the promotion of angiogenesis and metabolic reprogramming." (PMID 39697237, 2024). "HIF-1α activation in CRC was demonstrated to play a key role in tumor progression and can be used as a prognostic biomarker for the unfavorable course of the disease." (PMID 39063041, 2024).
tumor (continued). "On one hand, dexmedetomidine has been shown to promote angiogenesis and tumor growth by increasing HIF-1α and VEGF levels and activating the PI3K/AKT and MAPK pathways." (PMID 39766169, 2024). "Another study using B16-F10 injection found tumor-specific HIF-1α deletion enhanced CD4+, CD8+, and NK cell infiltration." (PMID 38426087, 2024). "In colon cancer HCT116 cells and tumor tissue under hypoxia (1% O2), miR-22 expression decreases and is positively correlated with the upregulation of HIF-1α and VEGF expression." (PMID 38766303, 2024). "HIF1α, a transcription factor essential for tumor adaptation under hypoxic conditions, drives pathways involved in angiogenesis, metabolism, and cellular survival." (PMID 39697237, 2024). "Accumulated studies confirm that hypoxia potently induces HIF-1α-dependent PD-L1 expression on tumor cells, suggesting that PD-L1 expression can be upregulated in hypoxic tumor cells to promote immune escape from cytotoxic T cells." (PMID 39635522, 2024). "Computed tomography (CT) images demonstrated the effective tumor-targeting ability of LyP-1 on Bi2S3@Bi nanorods, while examination of HIF-1α expression in tumor tissues indicated successful alleviation of tumor hypoxia." (PMID 38544975, 2024). "Overall findings suggest that erianin modulates PD-L1 expression by preventing its interaction with HIF-1α while also exerting anti-tumor effects on angiogenesis and proliferation both in vivo and in vitro." (PMID 38751791, 2024). "HIF1α is pivotal in predicting treatment responses and disease outcomes, enhancing adaptability to hypoxic conditions that contribute to tumor progression and resistance." (PMID 39697237, 2024). "In such a situation, the tumor cell sustains due to the transformation of the glucose metabolism pathway, which is, again, upregulated by the HIF-1α pathway." (PMID 39459028, 2024). "Recent studies revealed that HIF-1α-dependent genes play a crucial role in the rapid adaptation of tumor cells under hypoxic conditions by reprogramming the cellular metabolism." (PMID 38542288, 2024). "Previous studies demonstrated that tumour development and maintenance are supported by NF-κB, while cellular proliferation and adaptableness to angiogenic signals are assisted by HIF-1α." (PMID 38698968, 2024). "HIF1A (Hypoxia-inducible factor 1-alpha), a molecular marker plays a crucial role in embryonic vascularization and tumor angiogenesis, and it is often upregulated in human cancers through both hypoxic and non-hypoxic pathways and gene alteration as well." (PMID 39458948, 2024). "Higher levels of HIF-1α expression are associated with the NLRP3 inflammasome, EMT/metastasis, and Warburg effect in tumor cells." (PMID 38904007, 2024). "Strikingly, HIF1α linear ubiquitination was evident in tumor tissues from nude mice inoculated A549HOIPCON cells and further enhanced in A549HOIPOE tumors, strengthening our findings achieved with cultured cells and cell free system presented earlier." (PMID 38272870, 2024). "Hypoxia is a common feature in solid tumors and enhances tumor aggressiveness by increasing glycolytic activity in tumor cells through the activation of the hypoxia-inducible factor 1α (HIF1α) pathway." (PMID 39000386, 2024). "In cancer for instance, lactate uptake from the tumour microenvironment promotes macrophage polarisation through stabilising the HIF-1a transcription factor." (PMID 38521183, 2024). "The right tumor and left healthy tissues were further sectioned and subjected to staining with hypoxia-inducible factor 1α (HIF-1α) to detect hypoxia." (PMID 39613774, 2024). "SIRT3 acts as a tumor suppressor by destabilizing HIF-1α, thereby inhibiting these oncogenic processes." (PMID 39682281, 2024). "The anti-tumor mechanism of MLT is primarily to inhibit tumor angiogenesis by inhibiting the HIF-1α/VEGF signaling pathway." (PMID 39204162, 2024). "Of all the targets, PDE4D and more significantly, HIF1A showed high expression in ER-negative miR-18a/low tumours." (PMID 38786043, 2024).
tumor (continued). "HIF-1α upregulates PD-L1 on both tumour and stromal cells, whilst its receptors PD-1, CTLA-4 and LAG3 are all expressed on immune cells." (PMID 38352889, 2024). "Glycolysis reprogramming is an essential component of cancer cells’ metabolic adaptation, and it has been reported to be involved in the activation of key molecular pathways such as the PI3K/AKT/mTOR pathway, and the HIF-1α pathway in tumor progression." (PMID 38645412, 2024). "Hypoxia-inducible factor-1α (HIF-1α) has been reported to be ISGylated upon IFN treatment, which reduces the transcriptional activity of HIF-1α and subsequently affects tumor growth." (PMID 38443596, 2024). "HIF-1α overexpression inhibited human NK cells by downregulating the NK-cell-activating receptors involved in the tumor killing." (PMID 38892084, 2024). "Accumulative evidence points to a close relation between tumor hypoxia signaling and the angiogenic process depending on HIF-1α transcription of ILs, VEGF, and other factors." (PMID 38313904, 2024). "In contrast, inhibition of miR‐210‐3p in HIF‐1A‐overexpressed cells markedly restored monocyte migration, highlighting a direct link between the miR‐210‐3p level and tumor monocyte burden." (PMID 35658112, 2024). "The transcription factor HIF-1α plays a crucial role in regulating genes related to angiogenesis and the Warburg effect, both of which contribute to tumor formation." (PMID 39411137, 2024). "In the hypoxic environment triggered by solid tumors, HIF-1α is stably present and activates the transcription of tumor invasion-related genes, thus fostering tumor progression and chemotherapy resistance." (PMID 37588219, 2024). "They employed B16.F10 melanoma tumours and demonstrated that liposomes containing simvastatin significantly suppress the development of tumours by blocking the intratumor production of HIF-1α." (PMID 38707383, 2024). "Hypoxia is a condition that supports tumor growth and progression having an inadequate supply of oxygen through the activity of HIF1α." (PMID 39041636, 2024). "Considering the established role of the Akt signaling pathway and the HIF-1α signaling pathway in tumor angiogenesis, we detected the impact of ETHE1 on these two signaling pathways." (PMID 39198402, 2024). "On the other hand, ncRNAs can affect the adaptation and immune escape ability of tumor cells in hypoxic microenvironments by targeting the expression or signaling of hypoxia-inducible factors (e.g., HIF-1α) or tumor suppressors." (PMID 39555076, 2024). "Angiogenesis is initiated by the binding of VEGF secreted by hypoxic tumor cells under the control of hypoxic-inducible factor 1 (HIF-1α) to VEGF-R2 on endothelial cells." (PMID 39272798, 2024). "In this context, HIF1α stabilization seems to directly contribute to tumor growth, presumably endowing the tumor mass with the metabolic flexibility necessary to adapt to oxygen fluctuations." (PMID 38904014, 2024). "For instance, radiation-induced hypoxia, caused by damaged blood vessels within tumours, can lead to increased VEGF production through the activation of hypoxia-inducible factor 1-alpha (HIF-1α)." (PMID 39498386, 2024). "It is also interesting and proves our results that HIF1A expression appears to be enhanced in HNSCC cell lines derived from metastatic tumor sites." (PMID 38928200, 2024). "First, despite still showing an upregulation of HIF-1α in 40% of cases (versus 56% in tumor samples), the RQ expression levels were significantly lower in the peritumoral tissue when compared to the tumor tissue (Wilcoxon test, p = 0.03, z = 2.16)." (PMID 38607072, 2024). "The results from an in vivo study on female BALB/c nude mice indicated that britannin significantly inhibited the growth of HCT116 cells along with notable reductions in the tumor size as well as levels of HIF-1α, Myc, PD-L1, and VEGF in tumor tissues." (PMID 39690423, 2024).
tumor (continued). "The researchers further reported that the difference between high‐ and low‐Gleason grade PCa tumours was attributable to the activation of an EMT dedifferentiation programme driven by the HIF‐1α/VEGF/neuropilin‐1 pathway." (PMID 39632396, 2024). "Activation of HIF-1α in tumor cells leads to the upregulation of genes involved in angiogenesis, glycolysis, and cell survival, promoting tumor growth and metastasis." (PMID 39582869, 2024). "Immunohistochemistry and molecular assays represent standard methodologies for quantifying HIF1A levels, facilitating the assessment of tumour hypoxia." (PMID 39001444, 2024). "The study also found that positive HIF-1α staining was detected predominately in viable tumor cells in the tumor peripheral zone, which displayed a distribution pattern similar to that observed in hypoxic areas marked by pimonidazole." (PMID 39204162, 2024). "In the PC transplantation model, gemcitabine can reduce the protein levels of VEGF, VEGFR2, platelet and endothelial cell adhesion molecule 1 (CD31, PECAM1) and HIF-1α to reduce blood vessel formation, thereby reducing tumor growth." (PMID 38725864, 2024). "HIF1α is a key regulator in the adaptation of cancer cells to hypoxic conditions commonly found in tumor microenvironments and plays important roles in metabolic reprogramming, cell migration, stem cell renewal, and angiogenesis." (PMID 38339062, 2024). "Hypoxia, which acts through ROS delivery and HIF-1α stabilization, is a key determinant of human tumor progression." (PMID 38904007, 2024). "Future studies should focus on elucidating the specific mechanisms through which HIF-1α in ICs influences tumor progression and its potential as a prognostic marker." (PMID 39202223, 2024). "CA IX, like HIF-1α, is a major marker of hypoxic state in tumor cells and is used in tumor cell prognosis." (PMID 38474004, 2024). "HIF1α-driven changes promote cellular adaptation, contributing to increased tumor aggression and resistance to therapy." (PMID 39697237, 2024). "Examining the roles of SMURF2 and HIF1α in different cancers reveals their complex contributions to tumor progression and potential as therapeutic targets." (PMID 39697237, 2024). "During intermittent hypoxia and hypoxia-induced EMT, HIF1α serves a central role in enhancing the aggressiveness of tumor cells by regulating numerous genes involved in EMT." (PMID 38361941, 2024). "infantis + radiation significantly reduced HIF-1α expression, substantially reducing tumor hypoxia and enhancing radiosensitivity." (PMID 39030525, 2024). "Together, these studies establish a pivotal role of T cell-intrinsic HIF1α signaling in governing anti-tumor immunity elicited by ICBs in different types of tumors." (PMID 39477954, 2024). "HIF1A and NF-κB can co-operatively activate genes involved in tumor growth, progression and metastasis, metabolic reprogramming, and resistance to chemotherapy." (PMID 38339304, 2024). "Subsequently, HIF-1α induces the transcription of Rab27a, which promotes the release of sEVs; in turn, this promotes tumor growth." (PMID 39683818, 2024). "Under hypoxia conditions, hypoxia-inducible factor HIF-1α promotes glycolysis of tumor cells, including BC." (PMID 38697993, 2024). "The VHL-defective lesions arising in the kidneys of VHL patients demonstrate an increase in HIF and HIF target genes, and mouse VHL–/– ccRCC xenograft experiments revealed a tumor-promoting role of HIF2α and a tumor-constraining role of HIF1α." (PMID 38360997, 2024). "Mechanically, DAB2IP interacted with the E3 ubiquitin ligase STUB1 via its PER domain, thus triggering STUB1 mediated HIF-1α ubiquitylation and degradation, and inhibit glucose metabolism and tumor progression." (PMID 38862467, 2024). "On the contrary, in the tumor microenvironment, hypoxia leads to the continuous accumulation of HIF-1α, making cancer cells continuously adapt to hypoxia." (PMID 38257813, 2024).
tumor (continued). "Ergo, there is a shift towards a “HIF switch” in the peritumoral mucosa in contrast to the tumor tissue, where HIF-1α holds the predominant role." (PMID 38607072, 2024). "Many reports link high tumour HIF-1α expression with a poor prognosis including meta-analyses of studies in brain (n=1,422), breast [BCa] (n=6,201), digestive system (n=5,964), hepatocellular [HCC] (n=3,570), and oral cavity (n=1,471) cancers." (PMID 38352889, 2024). "In conclusion, our study provides strong evidence supporting the significance of HIF-1α stabilization through PHD2/3 deletion within CD8 T cells as an effective approach to enhance the anti-tumor response of CD8 T cells." (PMID 39242595, 2024). "They linked HIF-1α to VEGF-A expression, one of the important mechanisms for tumor angiogenesis, suggesting that the HIF-1a/VEGF-A axis is essential for tumor immunity." (PMID 39202223, 2024). "Hypoxia-inducible factor-1α (HIF-1α), produced in the hypoxic tumor microenvironment (TME), is closely associated with tumor metastasis." (PMID 39494330, 2024). "Transcriptional analyses of metformin-treated mouse bone marrow-derived macrophages show decreased expression levels of pro-tumour genes, including Tgfbi and Il1β, related to enhanced mTOR/HIF1α signalling and metabolic rewiring towards glycolysis." (PMID 39315158, 2024). "This disturbance ultimately prevents the activation of HIF-1α target genes, thereby inhibiting tumor growth." (PMID 39273204, 2024). "Hypoxia-inducible factor-1α (HIF-1α) is involved in tumor cell metastasis because it is a crucial transcription factor that regulates oxygen homeostasis." (PMID 39113883, 2024). "In tumor resection specimens of EC patients, the overall percentages of FAK+, CD44+, HIF-1α+, and Ki67+ cells were higher in tumor nests than in the tumor stroma, with the outcome for Ki67+ cells reaching statistical significance (p < 0.001)." (PMID 38727811, 2024). "HIF-1α regulates a variety of immune cells (such as T lymphocytes, macrophages, MDSCs) to modulate tumor immunity." (PMID 39464313, 2024). "Under reduced oxygen tension, tumor cells adapt to hypoxia and activate several survival pathways, including hypoxia factor 1α (HIF-1α) and vascular endothelial growth factor (VEGF), able to generate a vicious cycle with immune cells." (PMID 38339244, 2024). "Hepatocytes respond adaptively to the pathological environment of progressive hypoxia by upregulating the transcription factor HIF1A, thereby promoting the malignant transformation of hepatocytes into transitional and tumour cells." (PMID 37994257, 2024). "In response to tumor hypoxia, HIF-1α is stabilized, resulting in the upregulation of pro-angiogenic factors, including VEGF, PDGF, and FGF-2." (PMID 39057155, 2024). "In our in vivo experiments, we further confirmed that TAM-EVs enhanced HNSCC angiogenesis and tumor growth through the miR-21-5p/YAP1/HIF-1α axis." (PMID 38602536, 2024). "In the hypoxic tumor microenvironment, HIF-1α can adapt tumor cells to the hypoxic environment and induce angiogenesis by activating almost all glycolytic enzyme-related genes and angiogenesis-related genes." (PMID 38560503, 2024). "Then, by antagonizing c-myc, HIF-1α promotes glycolysis as the main metabolic pathway used by the tumor cells." (PMID 39763643, 2024). "Targeting HIF-1α in cancer therapy disrupts these adaptive mechanisms, inhibiting tumor progression and improving treatment outcomes." (PMID 39407697, 2024). "PD-L1 upregulation under hypoxia was directly dependent on hypoxia-inducible factor-1α (HIF-1α)—where it increased PD-L1 expression on macrophages, dendritic cells, and tumor cells." (PMID 38786085, 2024).